GPX4 (glutathione peroxidase 4)
Diseases named in the same sentence as GPX4 in open-access papers (continued):
Sharing a sentence is not in itself a finding about the gene and the disease.
tumor (continued). "Additionally, western blotting validates the expression of FTH1, GPX4, SLC7A11, FSP1 and DHODH in fresh surgical tumour tissues from three imatinib‐resistant patients compared with three imatinib‐sensitive patients receiving neoadjuvant imatinib therapy." (PMID 40866937, 2025). "For instance, although inhibition of GPX4 increases intracellular lipid peroxidation products and triggers ferroptosis in tumor cells, it simultaneously enhances PGE2-mediated immune evasion, fostering tumor progression." (PMID 39949740, 2025). "Furthermore, GPX4 is elevated in malignant tumors compared to benign specimens and is negatively correlated with TSPO expression in tumor specimens." (PMID 40842566, 2025). "In addition, the granule enzyme B released by CD8+ T cells inactivates GPX4 by cleaving its C-terminal domain and degrades ferroptosis suppressor protein 1 (FSP1), resulting in a collapse of the tumor cell’s antioxidant defense system." (PMID 40535125, 2025). "(2024) highlighted the regulatory role of ferroptosis in EMT-driven tumor resistance and emphasized the importance of GPX4 and SLC7A11—mirroring our clustering results that identified “tumor microenvironment”, “resistance”, and these regulators as prominent themes." (PMID 40416987, 2025). "Despite this, inhibition of GPX4 activity in DLBCL revealed that there is a higher dependence upon this defense pathway than in normal B-cells, underscoring the potential for selective tumor targeting." (PMID 41173858, 2025). "However, DDR1 knockdown significantly reduced GSH levels and GPX4, SLC7A11 and ZEB1 expression and increased MDA and Fe2+ levels, as well as ACSL4, E‐cadherin, p‐YAP and p‐NF2 expression levels in tumour tissues." (PMID 40105492, 2025). "Interestingly, direct GPX4 inhibitors, such as RSL3, ML162, ML210, FIN56, and FINO2, have demonstrated promising anticancer effects in many tumor types." (PMID 40724837, 2025). "Furthermore, ferroptosis of Tregs induced by GPX4 inhibition, releases proinflammatory factors that promote DCs and CD8+ T-cells activation and enhance anti-tumor immune responses." (PMID 41339932, 2025). "Notably, I@P-ss-FRT plus near-infrared (NIR) achieved optimal tumor suppression, accompanied by decline of GSH/GPX4 and accumulation of lipid peroxides at tumor sites in vivo." (PMID 40744916, 2025). "In addition, IHC analysis of tumor sections revealed a dose-dependent reduction in the expression of SCD1, β-catenin, GPX4, xCT, FASN, and ACC1." (PMID 40070686, 2025). "In addition, NFE2L1 was recently shown to suppress ferroptosis in OSCC by transcriptionally upregulating HJURP, which stabilizes GPX4 and SLC7A11 expression and reduces lipid ROS accumulation, thereby promoting tumor growth and ferroptosis resistance." (PMID 41227330, 2025). "Western blotting from the tumor tissue corroborated these observations, showing diminished GPX4 levels without alterations in PRDX1 and PRDX2 expressions." (PMID 40645965, 2025). "Interestingly In addition, the GPX4 inhibitor RSL3 can impair the maturation and function of DCs and anti -tumor activity of NK cells." (PMID 41339932, 2025). "And the increase in tumor volume and weight in the RNLS overexpression group was correlated with the upregulation of GPX4 and GSH levels, further validating the hypothesis that RNLS drives tumor progression through pro-proliferation and anti-ferroptosis." (PMID 40799250, 2025). "Having discovered that the GSH/GPX4 antioxidant response limits EZH2i efficacy in ACC, we hypothesized that a similar mechanism dampened their effects in other tumor types." (PMID 40229247, 2025).
tumor (continued). "In summary, the natural compound trigonelline has been shown to suppress Nrf2–ARE signaling and enhance the efficacy of ferroptosis inducers such as artesunate and GPX4 inhibitors in cisplatin-resistant HNC cells, highlighting its potential as a tumor-selective Nrf2 antagonist." (PMID 40867889, 2025). "This primed CDKN2A null GBMs for ferroptosis and inhibition of GPX4 through RSL3 led to significant cell death in CDKN2A null but not CDKN2A WT tumours." (PMID 40136651, 2025). "Preclinical studies have demonstrated that HCC xenografts with high FSP1 expression exhibit reduced sensitivity to GPX4 inhibitors; however, simultaneous targeting of FSP1 markedly restores tumor vulnerability, underscoring the therapeutic potential of this pathway." (PMID 40862825, 2025). "Furthermore, organoids derived from patients have illustrated that the modulation of the macrophage-capping protein (MCP)-GPX4/HMGB1 pathway can instigate immunogenic ferroptosis, thereby presenting a novel strategy to bolster anti-tumor immune responses." (PMID 40427552, 2025). "We further confirmed by western blotting that IKE-treated TIPE2−/− tumor MDSCs profoundly enhanced the key ferroptosis defense proteins SLC7A11 and GPX4, but immensely lowered the main lipid peroxidation trigger protein ACSL4 when compared to IKE-treated WT tumor MDSCs." (PMID 39851538, 2025). "Similarly, in 29 HCC subjects from Austria, selenium levels and GPX4 expression were inversely correlated with serum levels of VEGF and IL-8 (two clinically significant indicators of HCC), as well as tumor size." (PMID 40806069, 2025). "Interestingly, 52% of tumor tissue samples with decreased PLAG1 levels also showed reduced GPX4 levels, whereas 79% of samples with increased PLAG1 levels showed elevated GPX4 expression." (PMID 38745179, 2024). "OPN overexpression could promote GPX4 level and decrease autophagy-related LC3II/I, Atg5 and Atg7 expressions in tumor cells, which was subsequently reversed by LY294002 administration." (PMID 38526702, 2024). "Recently, dual hypoxia-sensitive polymeric nanocarriers have been designed to sensitize hypoxic tumor cells to ferroptosis by depleting NADPH, GSH, and Trx, thereby inhibiting GPX4 activity and enhancing the efficacy of ferroptosis-inducing agents, specifically in hypoxic tumors." (PMID 39273090, 2024). "GPX4 and FTH1 are the symbols of iron death occurring in tumor cells." (PMID 38345573, 2024). "In the context of TNBC, the utilization of MOF@GOx@MnO2@PEG: MGMP could induce tumor cell ferroptosis by suppressing the expression of tumor cell GSH and GPX4." (PMID 38853203, 2024). "Consistent with our results in vitro, the expression of GPX4 protein in tumor was also down-regulated after treatment with CORM-3 but not RuCl3." (PMID 38263152, 2024). "Furthermore, the overexpression of FASN resulted in the upregulation of GPX4 and the downregulation of 4-HNE in tumor tissues, indicating an inhibition of ferroptosis." (PMID 39345091, 2024). "For instance, using small interfering RNAs (siRNAs) or short hairpin RNAs (shRNA) to downregulate GPX4 or SLC7A11 could sensitize tumor cells to ferroptosis and inhibit tumor growth." (PMID 39624080, 2024). "The non-metabolic role of CKB enhances the durability of GPX4, unveiling an intricate process through which tumor cells encounter ferroptosis." (PMID 39036600, 2024). "Adoptive cell therapy (ACT) using activated CD8+ T cells with genetic deletion of GPX4 also failed to enable antitumor immunity and subsequent tumor control." (PMID 38441967, 2024). "Furthermore, in the subcutaneous tumour xenograft model, the expression of USP14 and FASN were increased, while the protein levels of GPX4 were decreased in the group with GSTM3 overexpression." (PMID 38228715, 2024). "GPX4-specific knockdown of Treg cells inhibited tumor growth and prevented tumor immune escape without inducing significant autoimmunity." (PMID 39359721, 2024).
tumor (continued). "GPX4-driven ferroptosis specifically targeted the non-cycling tumor cell states, with upregulation of the canonical ferroptosis marker TfR solely in Top2a negative cells." (PMID 39192032, 2024). "The compound N6F11 can trigger tumor cell ferroptosis by ubiquitinating GPX4, without affecting the degradation of GPX4 in immune cells like T cells, NK cells, and neutrophil cells." (PMID 39614322, 2024). "The absence of inhibition of GPX4 can spur ferroptosis induction together with a rise in lipid ROS within cells, inhibiting tumor cell proliferative activity." (PMID 39573995, 2024). "In tumor cells, ATF3 can inhibit System Xc− expression, and inhibit GPX4 and induce ferroptosis." (PMID 39712490, 2024). "Furthermore, findings from an in situ tumor model demonstrated that epirubicin effectively reduced the proliferation of U87-derived tumor tissues in situ, as well as downregulating the expression of KI67, PCNA, and GPX4 in the tissues." (PMID 38561331, 2024). "TIIA could significantly reduce the levels of GPX4 and GSH in tumor tissues, and inhibited tumor growth through the downregulation of the PERK-ATF4-HSPA5 signaling pathway." (PMID 38611836, 2024). "Furthermore, IHC staining confirmed that PMX205 induced suppression of GPX4 expression, accumulation of 4-HNE, and inhibition of tumor growth." (PMID 39368999, 2024). "However, when GPX4 is highly expressed, combining ferroptosis inducers with DHODH inhibitors significantly increases ferroptosis levels in tumor cells." (PMID 39065721, 2024). "The utilization of PD-L1 blockers elicits the secretion of IFN-γ by CD8+T cells, leading to the inhibition of transcription and expression of SLC7A11 and SLC3A2, thereby reducing GPX4 production via the JAK1/STAT1 pathway and facilitating ferroptosis in tumor cells." (PMID 38853203, 2024). "Consequently, the tumor cells highly expressing NCF-1 obtained coincident accumulation of ROS and reduced glutathione (GSH) with expression of glutathione peroxidase 4 (GPX4), a quencher involved in ferroptosis." (PMID 39666242, 2024). "Oral administration of an ESA-rich oil attenuated xenograft tumor growth of wild-type, but not that of LAMP2A-deficient HT1080 cells, accompanied by increased lipid peroxidation, GPX4 degradation and cell death." (PMID 39643606, 2024). "We isolated the tumours and performed IHC analysis using ATG5, GPX4, NLRP3, and Ki-67 staining." (PMID 38499622, 2024). "Genes involved in glycolysis (ALDOA, LDHA, PGK1, PFKL, PGM1) and other metabolic processes (GPX4, PRDX4, ACO2, ASPH, IDH2, SQLE, NPC2, SPTSSA) were upregulated in primary tumor cells, suggesting that the metabolism in primary tumors was distinct from that in their matched metastasis." (PMID 39225101, 2024). "Additionally, inhibitors of several key metabolic enzymes, such as IDH1(Isocitrate Dehydrogenase 1), IDO1((Indoleamine 2,3-dioxygenase 1), GPX4(Glutathione Peroxidase 4), and NAMPT(Nicotinamide phosphoribosyltransferase), have shown good anti-tumor effects." (PMID 39578429, 2024). "Furthermore, when compared to the CHMm+NK group, the CHMm+RNK group displayed a significant increase in the positive rates of Caspase 3 and BAX cells in tumor tissue, along with a significant decrease in the positive rates of BCL-2 and GPX4." (PMID 38891683, 2024). "Furthermore, the intracellular iron levels for Gi-F-CAA treatment tumor tissues were substantially higher than that of other groups, indicating the enhanced endocytosis of Gi-F-CAA and subsequent binding with GPX4 by in vivo self-assembly." (PMID 38212623, 2024). "In conclusion, we found that OPN could promote tumor sphere formation and angiogenesis in TNBC by activating the PI3K/AKT/mTOR pathway to regulate GPX4-mediated anti-lipid peroxidation levels." (PMID 38526702, 2024).
tumor (continued). "Additionally, plant metabolites and derivatives can regulate ferroptosis by targeting SLC7A11, GPX4, and ACSL4 and influence the immune status in the tumor microenvironment, providing new insights and directions for TCMs in cancer treatment." (PMID 38292937, 2024). "Notably, the administration of Fer-1, a ferroptosis inhibitor, partially restored GPX4 levels, confirming that MS100 induces ferroptosis-mediated tumor cell death." (PMID 39665080, 2024). "In vivo and in vitro investigations show that GSHOD‐like activity of O‐Fe‐N4 can lead to GPx‐4 activity downregulation, and POD‐mimic ability can produce highly efficient ROS, and both synergistically make tumor cells undergo ferroptosis, apoptosis, and necrosis." (PMID 38946659, 2024). "Furthermore, IHC staining of mice xenograft tumours demonstrated that circIDE overexpression increased the level of RBMS1 and 4HNE, while Ki67 and GPX4 expression was decreased by circIDE overexpression." (PMID 36989117, 2023). "Some experiments on tumor cell lines have shown that after treatment with FIN56, although the amount of GPx4 decreases, its transcriptional levels increase, demonstrating that FIN56 does not act at the transcriptional level but in the post-translational phase, causing a depletion of GPx4." (PMID 38139106, 2023). "Treatment of parental cells and DTCs with the GPX4 inhibitors RSL3 and ML210, respectively, revealed massive death of DTCs with less effect on parental cells; similar results were found in a variety of tumours." (PMID 37483492, 2023). "An active GPx4 is a requirement of a functional CGAS-STING pathway, a vital immune signaling pathway that is activated in response to infection by DNA viruses and which is also involved in tumor surveillance." (PMID 37373256, 2023). "Overexpression of GPX4 inhibits ferroptosis in CD8+ T cells and simultaneously restores the production of cytotoxic cytokines in vitro or increases the number of tumor-infiltrating CD8+ T cells in vivo, thereby enhancing tumor control." (PMID 36937406, 2023). "In addition, flow cytometry analysis of tumor-infiltrating immunocytes indicated significantly decreased IFN-β and TNF-α levels in the Gpx4-KD group." (PMID 38065948, 2023). "Compound 47 efficiently downregulated GPX4 protein expression, rose cellular ROS levels and inhibited at 15 mg/kg (single dose; application route is not given) tumor growth (4.5‐fold) in a murine xenograft model of HepG2 cells." (PMID 36658724, 2023). "The tumor‐specific nanosensitizer switched from the “off” to “on” state to exert therapeutic efficacy at the tumor site under US irradiation, enabling the GSH‐activated sonodynamic process and concomitantly inducing downregulation of GPX4." (PMID 36594611, 2023). "The results above suggest that GPX4 knockdown may activate T-cell activity, leading to enhanced TIL infiltration and the type II TNF response to kill tumor cells." (PMID 37649598, 2023). "Synergistic therapy induces tumor cell ferroptosis by depleting GSH and inhibiting GPX4 expression." (PMID 37894410, 2023). "GPX4 and HIF-1 expression was dramatically decreased in the C820 NPs group, suggesting specific ferroptosis and amelioration of the hypoxic environment in tumor tissues following C820 plus laser treatment, hence promoting tumor regression." (PMID 37742011, 2023). "Depression of circIL4R abrogates oncogenesis and accelerates ferroptosis of HCC cells by sponging miR-541-3p to suppress the expression of GPX4, suggesting that circIL4R functions as a tumor promoter and a ferroptosis inhibitor in HCC via the miR-541-3p/GPX4 axis." (PMID 37124203, 2023).
tumor (continued). "The Western blotting analysis revealed that RSL3 does not significantly change the GPX4 protein level in the tumor cells." (PMID 36672246, 2023). "Consequently, expression of NFE2L2, GPX4 and other anti-ferroptosis genes was upregulated in RMC cells from the MVAC-treated tumour compared to TAL cells, whereas many pro-ferroptosis genes were higher expressed in TAL cells." (PMID 37236926, 2023). "Additionally, both GPX4 and 15-LOX have the ability to block VCAM1, which aids in the promotion of tumor spread and angiogenesis." (PMID 37598126, 2023). "By contrast, xenograft tumors from Dox-fed animals treated with sorafenib exhibited sustained DDX5 protein levels, absence of GPX4 induction, and reduced tumor weight in comparison to those without Dox administration." (PMID 38036507, 2023). "In addition, the expression of MDA in tumor tissue decreased after overexpression of CST1, while it increased again after the downregulation of GPX4; opposite effects were seen after down-regulation of CST1." (PMID 36369321, 2023). "Recently, it was confirmed that GPX4 inactivating agent not only inhibits triple negative breast cancer (TNBC) via promoting ferroptosis, but also reshapes the tumor microenvironment, thus turning the “cold” tumor of LAR-type TNBC into a “hot” tumor." (PMID 38065948, 2023). "Similar results can be observed by IHC staining of ACSL4, GPX4, and SLC7A11 in subcutaneous tumor." (PMID 37993428, 2023). "Interestingly, GPX4 knockdown significantly inhibited PD-L1 expression in MFC cells, while an increase in PD-L1 expression was observed in the subcutaneous tumor model." (PMID 37649598, 2023). "However, the effects of circIDE were further reversed by additional GPX4 overexpression for the expression of RBMS1, Ki67, GPX4, and 4HNE in xenograft tumours." (PMID 36989117, 2023). "Furthermore, different groups of nude mice were treated with FINs or chemotherapeutic agents during tumor proliferation, and it was found that the tumors in the KLF11-OE group regressed significantly compared to KLF11-NC+GPX4 and KLF11-OE+GPX4 groups." (PMID 37248295, 2023). "The ability of some tumor cells to proliferate without GPX4 has triggered the exploration of pathways other than GPX4 to prevent ferroptosis." (PMID 37408372, 2023). "Whether by controlling GPX4, FSP1, or GSH, microRNAs fundamentally influence tumor ferroptosis via the antioxidant system." (PMID 37240889, 2023). "Clinicopathologically, we also found that KLF11 was low expressed in the LUAD tumor tissues compared to adjacent normal tissues, and the level of KLF11 was negatively correlated with the expression of GPX4 but positively correlated with the prognosis of LUAD patients." (PMID 37248295, 2023). "Considering the resistance of SPY1 to GPX4 inhibitor RSL3 in NSC34 and different tumor cells, we believe that SPY1 and downstream pathways may be effective protectors against ferroptosis caused by GPX4 deletion." (PMID 36443440, 2023). "And high levels of Gpx4 inhibits ferroptosis in NPC, thereby promoting tumor growth." (PMID 38140616, 2023). "Therefore, increasing the expression of GPX4 and FSP1 can synergistically promote the ferroptosis of tumor cells." (PMID 37564215, 2023). "However, sorafenib blocks glutathione synthesis to inhibit glutathione peroxidase 4 (GPX4), which can clear lipid peroxide as a diverse route from ferritinphagy to boost ferroptosis in tumor cells." (PMID 37238916, 2023). "Using the GPX4 inhibitor, RSL3, we observed pronounced ferroptosis in LAR tumor cells." (PMID 36861444, 2023). "We wonder whether combining GPX4, NOX1, and FACL4 could complementarily present tumor ferroptosis status in CRC." (PMID 35855531, 2023). "A lack of the GPX4 gene can lead to lipid peroxide (LPOs) overaccumulation and ferroptosis, which boost IL-1β production and enhance T helper 17 (Th17) cells’ anti-tumor immune response." (PMID 37598126, 2023).